CD63 (CD63 molecule)
Diseases named in the same sentence as CD63 in open-access papers (continued):
Sharing a sentence is not in itself a finding about the gene and the disease.
myocardial infarction (2 papers, 2025). Gross necrosis of the myocardium, as a result of interruption of the blood supply to the area, as in coronary thrombosis. "More recently, we identified a peptide that targets cell surface CD63 which is strongly upregulated in activated cardiac fibroblasts as well as epicardial cells after myocardial infarction." (PMID 40141106, 2025).
ovarian tumor (2 papers, 2020 to 2021). "Protein and gene expression analyses support the presence of basophils (CCR3, CD123, FcεRI) and activated basophils (CD63, CD203c, tryptase) in ovarian tumors." (PMID 32645919, 2020). "Protein expression of markers of basophils (CCR3, CD123, FcεRI) and basophil activation (CD63, CD203c, tryptase) were identified in a proportion of ovarian tumors by IHC analyses." (PMID 32645919, 2020).
pancreatitis (2 papers, 2018 to 2025). Inflammation of the pancreas. "The Western blot analysis showed that our EVs from the clinical control, pancreatitis, and PDAC patients were positive for CD63 and CD9." (PMID 40003965, 2025).
peanut allergy (2 papers, 2016 to 2018). "Stimulation of hMCs (sensitized with sera from patients with peanut allergy) with the recombinant peanut proteins rAra h 1, rAra h 2, rAra h 3, and rAra h 6 also increased CD63 expression." (PMID 29518421, 2018). "Incubation of passively sensitized hMCs with increasing concentrations of peanut extract resulted in a dose-dependent expression of CD63 in patients with peanut allergy but not in atopic control subjects." (PMID 29518421, 2018).
periodontal disease (2 papers, 2021 to 2024). "This study has shown that increased salivary azurocidin and extracellular CD63 levels are associated with enhanced innate response in periodontal disease and can be considered biomarkers of neutrophil activation." (PMID 38813360, 2024). "The results of this study suggest that increased salivary AZU and CD63 levels could be associated with enhanced innate response in periodontal disease and serve as biomarkers of neutrophil activation." (PMID 38813360, 2024). "The aim of this study was to quantify salivary levels of AZU and CD63 as biomarkers of neutrophil activation in patients with periodontal disorders and investigate the relationship between these two biomarkers and clinical periodontal parameters." (PMID 38813360, 2024). "The role of various subpopulations of sEVs from different tetraspanin proteins (CD63+, CD9+, CD81+ subtypes) in periodontal disease has not been widely investigated and requires further elucidation." (PMID 33670900, 2021).
sarcoma (2 papers, 2017 to 2023). A usually aggressive malignant neoplasm of the soft tissue or bone. "In addition, we found significantly higher values of activated platelet-derived (CD62P- and CD63-positive) microvesicles in sarcoma patients with a history of VTE, which might be a prognostic factor for the occurrence of VTE in soft tissue sarcoma patients." (PMID 28784104, 2017). "We found significantly higher counts of activated platelet-derived (CD62P- and CD63– positive) microvesicles in soft tissue sarcoma patients with localized and metastasized disease with a positive history of VTE, compared to sarcoma patients without a history of VTE." (PMID 28784104, 2017).
Thrombocytopenia (2 papers, 2022 to 2023). A reduction in the number of circulating thrombocytes. "As a consequence of shear stress and the exposure of blood to non-biological substances in ECMO patients, thrombocytopenia and altered platelet function may occur due to decreased levels of adhesion receptors, activation markers and surface expression of CD62/CD63." (PMID 35268436, 2022).
thyroid cancer (2 papers, 2022 to 2025). "In the remaining samples, differential expression of CD63 was observed between pathologies., Serum from Graves’ disease patients contained significantly more CD63+ particles than serum from thyroid cancer patients (P < 0.05)." (PMID 41551612, 2025). "On the other hand, it was suggested that tetraspanin CD63 does not play a direct role in thyroid cancer." (PMID 35328683, 2022).
triple-negative breast carcinoma (2 papers, 2021 to 2023). An invasive breast carcinoma which is negative for expression of estrogen receptor (ER), progesterone receptor (PR), and human epidermal growth factor receptor 2 (HER2). "Eribulin and paclitaxel caused an intracellular accumulation of CD63, a tetraspanin component of sEVs, in late/multivesicular endosomes of triple-negative breast cancer cells, consistent with the disruption of endosomal sorting and exosome cargo loading in these cells." (PMID 34205051, 2021). "Patients with triple negative breast cancers (TNBCs) exhibited the lowest number of EVs in the sera; whilst the highest was detected in ER+HER2+ cancers; reflected also in the higher level of CD63+ vesicles found within the ER+HER2+ local tumour microenvironment." (PMID 37441083, 2023).
acute kidney injury (1 paper, 2024). Sudden and sustained deterioration of the kidney function characterized by decreased glomerular filtration rate, increased serum creatinine or oliguria. "A Western blot analysis of uEVs showed increased abundances of uEV-specific tetraspanin CD9 and tetraspanin CD63 in patients with acute kidney injury on the first postoperative day (p < 0.05 by Mann–Whitney test)." (PMID 39334890, 2024). "The discovery cohort showed elevated CD9, CD63, and uEV-AQP2 levels in urine from recipients with acute kidney injury compared to immediate allograft function." (PMID 39334890, 2024). "On day 29 post-transplant, the CD9 and CD63 abundances were not different between patients with acute kidney injury and immediate allograft function." (PMID 39334890, 2024).
acute-on-chronic liver failure (1 paper, 2022). Acute-on-chronic liver failure (ACLF) is an extreme condition during the natural history of chronic HBV infection, with a relatively high short-term mortality. "Meanwhile, CD63 is one of the indicators for assessing liver regeneration and prognosis in patients with acute-on-chronic liver failure." (PMID 35706505, 2022).
amyotrophic lateral sclerosis (1 paper, 2021). Amyotrophic lateral sclerosis (ALS) is a neurodegenerative disease characterized by progressive muscular paralysis reflecting degeneration of motor neurons in the primary motor cortex, corticospinal tracts, brainstem and spinal cord. "In the SOD1G93A transgenic mouse model of amyotrophic lateral sclerosis (ALS), when CD63 was labeled with GFP and miR-124a was labeled with Cy5 under the CaMKII promoter, the number of GFP puncta was not changed, but the colocalization ratio of GFP and Cy5 increased." (PMID 34638890, 2021).
B cell lymphoma (1 paper, 2021). "A study examining several B cell lymphoma cell lines found no CD9 expression and variable CD63 and CD81 levels." (PMID 33513976, 2021).
Basement membrane disease (1 paper, 2021). "We found that renal CD63 expressions were significantly up-regulated in patients with FSGS compared to those with thin basement membrane disease (TBMD)." (PMID 34708038, 2021).
bone metastasis (1 paper, 2019). Transfer of a neoplasm from its primary site to bones. "Case No. 14 showed bone metastasis with recovered levels of miR-21 and a normal range for MMP-1/CD63." (PMID 31537868, 2019).
brain injury (1 paper, 2025). Acute and chronic (see also brain INJURIES, CHRONIC) injuries to the brain, including the cerebral hemispheres, CEREBELLUM, and brain STEM. "A mouse experiment shows that TIMP1 regulates endothelial barrier integrity by interacting with CD63/integrin β1 complex and has a protective effect on BBB breakdown induced by traumatic brain injury." (PMID 40604895, 2025).
cardiac interstitial fibrosis (1 paper, 2025). "TIMP-1 - together with TIMP-2 - is correlated to the development of cardiac interstitial fibrosis, possibly mediating CD63-Integrin β1 interaction." (PMID 41467913, 2025).
cerebral small vessel disease (1 paper, 2023). Cerebral small vessel disease is the term currently used to pathological processes that affect the brain parenchymal circulation (arterioles, capillaries, and veins). "Future investigations could also query whether mutations in CD63 or CTSH are linked to human cerebral small vessel disease outside of CADASIL." (PMID 36753487, 2023).
Chediak-Higashi syndrome (1 paper, 2011). ChC)diak-Higashi syndrome (CHS) is a rare severe genetic disorder generally characterized by partial oculocutaneous albinism (OCA), severe immunodeficiency, mild bleeding, neurological dysfunction and lymphoproliferative disorder. "Hematopoietic cells from individuals with Chediak-Higashi Syndrome (CHS), a rare, autosomal recessive condition characterized by partial albinism, prolonged bleeding time and immune dysfunction, display abnormally large CD63+ SL that are unable to exocytose at the plasma membrane." (PMID 21909273, 2011).
chronic myeloid leukemia (1 paper, 2025). "This study revealed deregulation of asymmetric stem cell division markers during chronic myeloid leukemia (CML) progression, with pronounced downregulation of five key genes—CD63, SELL, NUMB, HK2, and LAMP2—during blast crisis compared to the chronic phase." (PMID 40868343, 2025).
colitis (1 paper, 2015). Inflammation of the colon. "These activated eosinophils in colitis also expressed the degranulation marker CD63." (PMID 26200014, 2015).
diffuse astrocytoma (1 paper, 2018). A low-grade (WHO grade II) astrocytic neoplasm. "In diffuse astrocytomas, CD63 was expressed by the tumor cells and the tumor blood vessels in 91% and 92% of the tumors, respectively." (PMID 29523123, 2018). "In diffuse astrocytomas with a gemistocytic pattern, tumor cells with distinct CD63 expression were observed, whereas a more diffuse CD63 staining was seen in tumors with a predominantly fibrillary pattern." (PMID 29523123, 2018). "Similar to the diffuse astrocytomas, CD63 appeared to be located in the apical endothelial membrane as well as in the cytoplasm of endothelial cells." (PMID 29523123, 2018).
eczema (1 paper, 2025). "For eczema and Pso, the appearance of CD63 and/or CD163 in combination with CD14 and/or CD1a and/or CD11c in eczema was most discriminatory." (PMID 41009640, 2025). "While in Pso a monocyte-derived DC (CD14+CD1a+CD11c+) predominated, possibly a Langerhans cell (LC)-like DC, eczema displayed a marker combination of a seemingly more differentiated monocyte-derived DC (CD14+CD63+CD163+), potentially a DC3 cell type." (PMID 41009640, 2025). "Conversely, in eczema these cells additionally expressed CD63 and CD163 in various combinations with CD1a and CD11c." (PMID 41009640, 2025). "In summary, CD14+ positive cells harbouring DC markers (CD11c, CD1a) in combination with CD63 and/or CD163 were far more present in eczema compared with Pso." (PMID 41009640, 2025). "For example, the marker combination CD14, CD63, and CD163 was 4.4-fold higher in eczema compared with Pso (~35 cells/mm2 vs. ~8 cells/mm2), and the marker combination CD11c, CD63, and CD163 was 8.4 fold higher (~25 cells/mm2 vs. 3 cells/mm2) (blue box)." (PMID 41009640, 2025). "Supporting this conclusion, the marker combinations CD11c, CD63, CD163 and CD14, CD63, CD163 were almost exclusively found in eczema." (PMID 41009640, 2025). "Triple marker combinations that included CD63 and/or CD163 were each somewhat less frequent in number; however, together they were the most frequent DC populations in eczema (grey bars), and significantly more prevalent than in Pso (black bars)." (PMID 41009640, 2025). "The differentiation of DC in eczema is potentially induced by bacterial-derived antigens (likely from Staphylococcus aureus), eventually leading to the expression of CD163 and CD63, although the latter marker has been described as being expressed on immature DCs." (PMID 41009640, 2025). "While Pso cells with DC markers maintained a CD14+, potentially LC-like phenotype (CD14+CD1a+CD11c+), cells in eczema displayed a marker combination that included CD163 and/or CD63, hinting at a more differentiated DC that may constitute a DC3 subtype, as previously suggested." (PMID 41009640, 2025). "In summary, the appearance of CD63 and/or CD163 on CD14+ and/or CD1a/CD11c+ cells were most characteristic and distinctive for eczema skin, whereas the same cells were lacking CD63/CD163 in psoriatic skin." (PMID 41009640, 2025). "However, marker combinations that included CD63 and/or CD163 were comparably present (ratios 15–20:1), making these marker combinations representative for eczema but not for Pso." (PMID 41009640, 2025).
endometritis (1 paper, 2022). An acute or chronic, usually bacterial infectious process affecting the endometrium. "The EVs from mares with endometritis differentially expressed CD9 and CD63, compared to controls." (PMID 35042518, 2022). "Interestingly, the EVs isolated from serum and LVL in mares with endometritis differentially expressed CD9 and CD63, compared to control healthy ones." (PMID 35042518, 2022). "Moreover, the EVs isolated from serum and LVL in mares suffering from endometritis were differentially expressed CD9 and CD63, compared to control healthy." (PMID 35042518, 2022).
fibrosis (1 paper, 2019). the formation of excess fibrous connective tissue in an organ or tissue in a reparative or reactive process. "TIMP1 and TIMP4 were both found to correlate inversely with suppressor of cytokine signaling 1 (SOCS1) expression in two in vitro fibrosis model systems and putatively shown to share CD63, an exosomal marker, as a binding partner in MMP-independent activities." (PMID 31765403, 2019).
food allergy (1 paper, 2021). Gastrointestinal disturbances, skin eruptions, or shock due to allergic reactions to allergens in food. "They reported a significant correlation between the %CD63+/anti‐FcεRI ratio and the outcome of the oral challenge test, depending on the ingested dose and reaction severity in patients with food allergy." (PMID 34386193, 2021).
gastric ulcer (1 paper, 2011). An ulcerated lesion in the mucosal surface of the stomach. "All normal gastric epithelium and gastric ulcer tissues strongly expressed transcripts of CD9, CD63 and CD82." (PMID 21521534, 2011). "All normal gastric epithelium and gastric ulcer tissues were strongly expressed immunostaning of CD9, CD63 and CD82." (PMID 21521534, 2011). "All normal gastric epithelium and gastric ulcer tissues strongly expressed transcripts and proteins of CD9, CD63 and CD82 as compared with corresponding controls." (PMID 21521534, 2011).
Glucose intolerance (1 paper, 2021). Glucose intolerance (GI) can be defined as dysglycemia that comprises both prediabetes and diabetes. "Next, we determined whether CD63+A33+ T2D-Exo from the stool of T2D human patients might elicit glucose intolerance and insulin resistance in C57BL/6 SPF mice." (PMID 33431899, 2021).
heart failure (1 paper, 2025). Inability of the heart to pump blood at an adequate rate to meet tissue metabolic requirements. "Interestingly, iron can induce CD63 expression 41, and treatment with intravenous iron in a clinical setting is known to reduce both cardiovascular death and heart failure-related events in a broad population." (PMID 39744226, 2025).
Hepatic steatosis (1 paper, 2015). Steatosis is a term used to denote lipid accumulation within hepatocytes. "Since hepatic overexpression of constitutively active Akt is known to induce hepatic steatosis, TIMP-1 may act through binding to CD63 and phosphorylation of Akt, thereby promoting hepatic steatosis." (PMID 26168159, 2015).
Hepatitis (1 paper, 2020). Inflammation of the liver. "We then investigated the effects of silencing Cd63 in the ConA-induced hepatitis model mice." (PMID 33221747, 2020).
hypercholesterolaemia (1 paper, 2024). "Our data show that CD63+ circulating EVs were statistically significantly decreased in hypercholesterolaemia patients compared to normocholesterolaemic patients." (PMID 39420340, 2024). "Similarly to the mouse models, CD63+ EV levels were significantly reduced in hypercholesterolaemia compared to normocholesterolaemic patients." (PMID 39420340, 2024). "This may further support that CD63+ EVs levels could assist clinicians in delivering a more accurate diagnosis to hypercholesterolaemia and overall cardiovascular health of patients." (PMID 39420340, 2024). "Similarly to mice, in patients with hypercholesterolaemia, CD63+ EVs were significantly depleted." (PMID 39420340, 2024).
hypercoagulation (1 paper, 2020). "Tamoxifen-treated T47D cells induced later stages of platelet activation associated with a loss of CD62P IPA and persistence of CD63 IPA reflecting hypercoagulation in both PRP and WB, compared to MCF7 cells." (PMID 33159119, 2020). "We determined a weak positive correlation between oestrogen receptor expression, and CD62P and CD63; indicating an association between tumour invasion profiles and hypercoagulation, however, other yet unknown factors may play a predictive role in defining hypercoagulation." (PMID 33159119, 2020).
Hyperglycemia (1 paper, 2023). An increased concentration of glucose in the blood. "Then, the secretion of SCO-spondin- and CD63-positive vesicles were increased in hyperglycemia, which was detected in the apex of ependymal cells." (PMID 37733692, 2023). "CD63 was also detected on ependymal cells only under hyperglycemia, where poor colocalization between CD63 and SCO-spondin was observed (arrowheads for SCO-spondin, white arrows for CD63, yellow arrows for colocalization)." (PMID 37733692, 2023).
hypertrophy (1 paper, 2020). Hypertrophy is the increase in the volume of an organ or tissue due to the enlargement of its component cells. "For example, CD63 and TSG101 were decreased in TAC EVs and these markers were previously reported to be involved in cardiac fibrosis and hypertrophy, respectively." (PMID 32485073, 2020).
kidney cancer (1 paper, 2022). Primary or metastatic malignant neoplasm involving the kidney. "This does not only suggest that CD63 plays a critical and specific role in kidney pathology, and consequently in kidney tumorigenesis, but also hints that CD63 can be a therapeutic target for kidney cancer with minimal systemic toxicity." (PMID 36542714, 2022). "It will be worth exploring whether anti-CD63 antibodies are able to improve the potency of targeted therapy or immunotherapy and inhibit metastasis in patients with kidney cancer." (PMID 36542714, 2022). "Moreover, in-depth annotations have revealed the pivotal role of CD63 on tumorigenesis in kidney cancer and the potential therapeutic application of anti-CD63 antibody on patients with kidney cancer." (PMID 36542714, 2022). "Moreover, we highlighted the pivotal role of CD63 as an oncogenic driver and a potential therapeutic target in kidney cancer." (PMID 36542714, 2022). "Hence, CD63 probably plays an oncogenic role in kidney cancer." (PMID 36542714, 2022). "Among the five core genes selected by SCOPE in kidney cancer (KIRC), CD63 plays an indispensable role in VEGFR2 activation in response to VEGF." (PMID 36542714, 2022).
kidney tumors (1 paper, 2022). "Along this line, high expression of CD63 in kidney tumors correlates with a hypoxia gene signature assessed by two different scores." (PMID 36542714, 2022).
liposarcoma (1 paper, 2021). A usually painless malignant tumor that arises from adipose tissue. "Therefore, the micro‐nanofluidic device integrates the unit operations of size‐based separation with CD63 antibody immunoaffinity‐based capture of extracellular vesicles in the same device to evaluate EV‐cargo content for liposarcoma." (PMID 33643547, 2021).
liver failure (1 paper, 2025). A liver disease characterized by the liver losing or has lost all of its function. "Targeting CD63+ ECs could provide new insights for developing effective therapies for drug-induced liver failure." (PMID 40355725, 2025).